RNU1-34P (RNA, U1 small nuclear 34, pseudogene)
Gene: Small nuclear RNA gene on chromosome 6 (75,473,738 to 75,473,894, reverse strand). Ensembl gene ENSG00000201291.
Homologues: Orthologues: chimpanzee U1 (92% identical), macaque U1 (87% identical), rabbit U1 (71% identical), dog U1 (61% identical). Paralogues in human: RNU1-1 (85% identical), RNU1-2 (85% identical), RNU1-21P (85% identical), RNU1-27P (85% identical), RNU1-28P (85% identical), RNU1-3 (85% identical), RNU1-4 (85% identical), RNVU1-18 (85% identical), RNVU1-29 (85% identical), U1 (85% identical), RNVU1-28 (85% identical), RNVU1-31 (85% identical), and 134 more.